PKD2 (polycystin 2, transient receptor potential cation channel)
Diseases named in the same sentence as PKD2 in open-access papers (continued):
Sharing a sentence is not in itself a finding about the gene and the disease.
end-stage renal disease (28 papers, 2012 to 2025). "PKD2 mutations tend to manifest in older individuals, presenting with milder symptoms, fewer kidney cysts, delayed hypertension onset, and less frequent end-stage renal disease than PKD1 mutations." (PMID 38989164, 2024). "In the previous study on genetic analysis of ADPKD-diagnosed families, patients with IFT140 pathogenic variants had a milder chronic kidney disease course than those with PKD2 pathogenic variants." (PMID 39291187, 2024). "The renal survival rate of ADPKD patients with PKD1 mutations (77/112) was significantly lower than that of those with PKD2 mutations (9/16), leading to an earlier onset of end-stage renal disease (ESRD)." (PMID 36186434, 2022). "Mutations within PKD1 gene are reportedly associated with earlier onset of end-stage renal disease when compared to those with PKD2 mutations." (PMID 35629189, 2022). "PKD2 mutation causes end-stage renal disease at an average age of 74 years, which occurs in 10–15% of cases; on the other hand, PKD1 mutation results in end-stage renal disease at an average age of 54 years which occurs in 80–90% of total cases of ADPKD." (PMID 32957937, 2020). "The two causative genes are PKD1 and PKD2, and end-stage renal disease (ESRD) tends to occur around 53 years of age in patients with PKD1 and 68 years of age in patients with PKD2, respectively." (PMID 32178226, 2020). "A grandmother with the PKD1 gene mutation in mosaicism (p.Val1105ArgfsX4) and with mild clinical course of ADPKD (end stage renal failure at the age of 77) seemed to have ADPKD because of PKD2 gene mutation." (PMID 23496908, 2013). "Patients with PKD2 mutation have a later onset of disease and develop end-stage renal failure later than those with PKD1 mutation." (PMID 23304619, 2012). "While specific longitudinal data on PKD2 truncating variants are limited, PKD2 mutations in general are associated with milder ADPKD, where midlife onset of end-stage renal disease is delayed 10–15 years compared with patients who carry PKD1 mutations." (PMID 41212053, 2025). "Mutation either in the PKD1 (approximately 85% of patients) or PKD2 gene (approximately 15%) cause ADPKD, with an average age of 54.3 and 74 years, respectively, at the onset of ESRD (end stage renal disease)." (PMID 23496908, 2013). "To determine whether this pathway has translational relevance, we examined tissue from 3 normal human kidneys, a patient with a known PKD2 mutation, and 3 patients who likely have a PKD1 mutation based on the age of onset of end-stage renal disease (ESRD)." (PMID 40763312, 2025). "Additionally, 50% of the studied PKD1/PKD2 affected individuals reached a high disease grade (G4/5) or end-stage renal disease (ESRD)." (PMID 36422197, 2022). "The proband, with an extremely serious manifestation of ADPKD (the man was diagnosed in early childhood, and with end stage renal disease aged 23), underwent genetic analysis of PKD1 and PKD2, which revealed the presence of pathogenic mutations in both of these genes." (PMID 29973168, 2018). "Genotype-phenotype correlations showed that patients with PKD1 variants predicted to truncate (T) the protein experienced end-stage renal disease 9 years earlier than patients with PKD1 non-truncating (NT) mutations and >13 years earlier than patients with PKD2 mutations." (PMID 32457805, 2020).
kidney failure (26 papers, 2008 to 2026). An acute or chronic condition that is characterized by the inability of the kidneys to adequately filter the blood. "Both 75-year-old women carrying a truncating PKD2 variant reached kidney failure at the age of 58 and 60 years, respectively." (PMID 41502815, 2026). "Generally, mutations in PKD2 are associated with a later onset and a slower progression to renal failure compared to those in PKD1." (PMID 41294622, 2025). "Mice heterozygous for a mutation in Pkd2 also develop kidney cysts and renal failure and die as young adults." (PMID 28271061, 2017). "The error possibilities calculated using genotyping error simulation method in screening known causative genes PKD1 and PKD2 for a family with renal failure with the genotype data of patient s1 and s4." (PMID 19399176, 2009). "The effect of using subsets of the affected individuals (s1, s2, s3 and s4) and different cutoff values in the screening of the known causative genes PKD1 and PKD2 for a family with renal failure." (PMID 19399176, 2009). "Furthermore, in contrast to previous studies suggesting that PKD1 and PKD2 are the most common genetic causes of kidney failure, our findings indicate that among Bedouins, COL4A3 variants are the predominant genetic etiology." (PMID 40303201, 2025). "Genetic factors, particularly pathogenic variants in PKD1 and PKD2, have been strongly associated with disease severity, with truncating PKD1 mutations leading to earlier onset of kidney failure." (PMID 41294622, 2025). "Variations in PKD1 are generally associated with a more severe disease course and an earlier onset of kidney failure compared to those in PKD2." (PMID 40565535, 2025). "Among the top predictions in zebrafish are genes associated with human diseases including Parkinson’s disease (PARK7), cancer (APC, a known tumor suppresion gene) and kidney failure (PKD2)." (PMID 36158574, 2022). "Heterozygous, pathogenic loss-of-function variants in either PKD1 or PKD2 are the primary cause of typical ADPKD, which is characterised by development of progressive macroscopic kidney cysts that cause massively enlarged kidneys and kidney failure." (PMID 41006799, 2026). "Furthermore, patients who identified with PKD2 and COL4A1 mutations developed kidney failure earlier than those with monogenic disorders." (PMID 41557100, 2026). "However, genetic analysis showed that neither of his parents (VI:19 nor VI:20) or the paternal grandmother had the PKD2 mutation, and so the renal failure was not PKD related and most likely due to reflux nephropathy." (PMID 24011172, 2013). "Disease caused by mutations in PKD1 is usually correlated with a worse outcome and kidney failure at a mean age of 56 years (55.6 years if the genetic variant is truncating, versus 67.9 years if non-truncating), as opposed to the PKD2 phenotype with a mean age of 77 years at onset of kidney failure." (PMID 39574911, 2024).
Kidney Cyst (22 papers, 2008 to 2025). Abnormal fluid filled sac within the kidney, either acquired or congenital. "Of 157 patients, 7 had parents with simple kidney cyst (1 with the IFT140 pathogenic variant, 3 with the PKD1 or PKD2 pathogenic variant, 1 with the OFD1 pathogenic variant, and 2 without pathogenic variants)." (PMID 39291187, 2024). "In patients with the diagnosis of PKHD1, ALG8, and GANAB variants, kidney cysts tend to be less destructive than PKD1 and PKD2 with relatively preserved kidney contours." (PMID 35778421, 2022). "We investigated JNK’s role in promoting cysts due to Pkd2 loss and found that disrupting JNK signaling reduced kidney cysts in juvenile mice and liver cysts in adult mice." (PMID 34962918, 2021). "We expect that Pkd2 mutants would develop kidney cysts at older ages based on evidence from Pkd1 models, but severe liver findings precluded further aging." (PMID 34962918, 2021). "Previous studies have demonstrated that further postnatal reductions in PKD1 (or PKD2) dose are required for kidney cyst formation, which can be induced by DNA damage, and activation of the DNA damage response pathway." (PMID 32724471, 2020). "Consistent with previous reports, we find that repression of either Pkd1 or Pkd2 results in obvious kidney cysts within two months after removal of doxycycline." (PMID 29443690, 2018). "Previous work demonstrated that the human ADPKD kidney cyst phenotype can be reproduced in mice 14 weeks after conditional ablation of nephron-localized Pkd1 or Pkd2." (PMID 29443690, 2018). "Knockdown of MFN2 restored defective mitochondrial calcium ion transfer and reduced cell proliferation in mouse with kidney cysts, suggesting that PKD2 acts as a regulator of mitochondrial biogenesis and bioenergetics by regulating essential mitochondrial proteins at the ER–mitochondrial junction." (PMID 39451240, 2024). "Treating Pkd2 flox (fl) homozygotes (Rosa26-CreERT2; Pkd2fl/fl) resulted in extensive kidney cysts." (PMID 34962918, 2021). "In compound heterozygous Pkd2−/poreL1 mice no wild-type Pkd2 allele and only one Pkd2poreL1 allele will be present, so that these animals may be more prone to developing kidney cysts than the Pkd2poreL1/poreL1 mice." (PMID 34345895, 2021). "Typically, PKD1 patients have greater htTKV than PKD2 patients, and although PKD1 and PKD2 kidneys increase in size at the same rate, PKD1 patients have 40% more detectable kidney cysts." (PMID 38156331, 2023). "PKD1 and PKD2 variants are linked to ADPKD regardless of the presence or absence of PLD, while PRKCSH and SEC63 variants are always associated with ADPLD without kidney cysts." (PMID 37761895, 2023). "Pkd2 mutants aged 6 months showed no signs of kidney cysts in histological sections or by 2-kidney to body weight ratios." (PMID 34962918, 2021). "Polycystic liver disease is the most common extrarenal ADPKD symptom Interestingly, despite lacking kidney cysts, adult Pkd2 mutants contained numerous biliary liver cysts." (PMID 34962918, 2021). "Whereas kidney cyst development with ADPKD is well-established, pathologies caused by mutations to PKD2 do not exclusively affect the kidneys." (PMID 31941974, 2020). "Development of PKD-type kidney cysts was apparent in all (10/10) of the induced cPkd2 mice after one year, whereas none of the Pkd2+/+ (0/18), Pkd2+/del-Z (0/19) and Pkd2del-Z/del-Z (0/18) animals developed PKD-type cysts." (PMID 33199522, 2020). "We further show that Pkd2lrm4/lrm4 embryos develop kidney cysts that proved indistinguishable from those of Pkd2−/− embryos." (PMID 31492868, 2019). "94% of ADPKD patients develop hepatic cysts by their fourth decade, but most remain asymptomatic Rarely, severe liver involvement requires surgery to reduce liver volume In our adult model of Pkd2 deletion, we found extensive liver cysts after six months, without detectable kidney cysts." (PMID 34962918, 2021). "Mirroring kidney cysts, Polycystin-2 was no longer detected along pkd2-morphants KV cilia." (PMID 26432887, 2015).
Kidney Cyst (continued). "However, limiting its usage to study the ADPKD cystogenesis, cup−/− mutants do not develop kidney cysts, probably because of the maternal contribution of pkd2 mRNA present during early embryonic stages." (PMID 26432887, 2015).
Hypertension (20 papers, 2012 to 2025). The presence of chronic increased pressure in the systemic arterial system. "Additionally, PKD1 mutation carriers generally have a poorer renal prognosis and develop hypertension earlier than PKD2 mutation carriers." (PMID 39457385, 2024). "Having established that myocyte PKD2 channels regulate arterial contractility and systemic blood pressure, we investigated whether hypertension is associated with an alteration in PKD2 expression, surface protein and function." (PMID 30511640, 2018). "Furthermore, we show that hypertension is associated with an increase in plasma membrane-resident PKD2 channels." (PMID 30511640, 2018). "We also show that PKD2 channels are upregulated during hypertension and that myocyte PKD2 knockout causes vasodilation, attenuates remodeling of the arterial wall and reduces high blood pressure during hypertension." (PMID 30511640, 2018). "We tested the hypothesis that arterial myocyte PKD2 channels are associated with the increase in blood pressure during hypertension." (PMID 30511640, 2018). "The finding that the gene collapsing analyses in essential hypertension identified variation in genes (PKD1, PKD2, COL4A4, UMOD, CACNA1D, and NR3C2) that are possible causes of undiagnosed secondary hypertension is worthy a special comment." (PMID 37059828, 2023). "ADPKD is typically characterized by the growth of renal cysts, although a significant proportion of patients develop hypertension prior to kidney dysfunction, suggesting PKD2 channels perform physiological functions in vascular wall cell types." (PMID 32364494, 2020). "In summary, our study indicates that PKD2 channels in systemic artery myocytes control physiological blood pressure and are upregulated during hypertension, contributing to the blood pressure elevation." (PMID 30511640, 2018). "Our data demonstrate that myocyte PKD2 channels are upregulated during hypertension and that PKD2 targeting reduces vasoconstriction, blood pressure and arterial remodeling during hypertension, eliciting multi-modal benefits." (PMID 30511640, 2018). "We also show that arterial myocyte PKD2 channels are upregulated during hypertension and genetic knockout reduces high blood pressure." (PMID 30511640, 2018). "Inducible, smooth muscle cell-specific PKD2 knockout lowers both physiological blood pressure and hypertension and prevents pathological arterial remodeling during hypertension." (PMID 30511640, 2018). "PKD2 is usually significantly milder than PKD1 with development of ESRD at a later age and a lower prevalence of arterial hypertension and urinary tract infections." (PMID 29479522, 2017). "The USRDS also does not have information on ADPKD genotype, and we thus cannot distinguish between genotype PKD1 vs. genotype PKD2, which generally has a more indolent course than PKD1, ie later age at diagnosis, and later onset of hypertension and ESRD." (PMID 24571546, 2014). "PKD2), early onset of hypertension or urological events, these have not been validated in children, and probably need to be refined further." (PMID 33677691, 2022). "Left ventricular hypertrophy (LVH, prevalence 30%) was significantly associated with PKD1 mutations (PKD1 non-truncating versus PKD2 adjusted P-value = .011; PKD1 truncating versus PKD2 adjusted P-value = .011), independent of hypertension, age, sex and anaemia (adjusted OR 8.5, P = .008)." (PMID 41195291, 2025).
ciliopathy (19 papers, 2015 to 2025). A genetic disorder of the cellular cilia or the cilia anchoring structures, the basal bodies, or of ciliary function. "Autosomal-dominant polycystic kidney disease (ADPKD) is a ciliopathy caused predominantly by mutations in the PKD1 or PKD2 gene, encoding for polycystin 1 (PC1) and PC2, respectively." (PMID 40814262, 2025). "Variants in PKD1 and PKD2 comprised 85.3% of the positive findings in this group, and other ciliopathy-associated genes (ALG9, PRKCSH, OFD1) accounted for an additional 3%." (PMID 37794564, 2023). "The Paramecium Pkd2 and its partner XntA1 broaden the possibilities for interacting partners, functions of these partners, and locations of ciliopathy proteins." (PMID 34680887, 2021). "It is plausible that the therapeutic outcome of intervening with PD-1|PD-L1 signaling may differ when using other models of PKD such as germline Pkd2 or ciliopathy models, as well as inducible kidney-specific Pkd1 or Pkd2 knockout models." (PMID 37345660, 2023). "We showed that RNAi depletion of BBS gene products leads to loss of ciliary K channels and another ciliopathy channel (PKD2), but not other ion channels and sensory proteins from the cilia." (PMID 34680887, 2021). "A human ciliopathy gene codes for Polycystin-2 (Pkd2), a non-selective cation channel." (PMID 31207979, 2019).
breast carcinoma (17 papers, 2013 to 2024). "Taken together, we characterized the oncogenic functions of PKD2/3 in breast cancer and their association with cancer‐related pathways, which shed lights on the oncogenic roles and mechanisms of PKDs in breast cancer." (PMID 30652415, 2019). "Taken together, the overall consistence between PKD2‐, PKD3‐, and PKD2&3‐regulated phosphoproteins in their reactome profiles, enriched pathways and hub‐nodes indicated the underlying mechanisms of the oncogenic roles of PKD2 in breast cancer." (PMID 30652415, 2019). "Previous studies have shown that knockdown of PKD2 markedly inhibited breast cancer cell migration and invasion." (PMID 39408603, 2024). "In highly invasive breast cancer, loss of PKD1 appears to promote invasion and metastasis, whereas PKD2 and upregulated PKD3 positively influence proliferation, chemoresistance and metastasis." (PMID 37293129, 2023). "In order to identify the PKD2-regulated signaling pathways that mediate its oncogenic functions in breast cancer, Liu Y and collaborators performed an integrated phosphoproteome, transcriptome and interactome analysis." (PMID 35805075, 2022). "ELAVL1 silencing impairs in vitro and in vivo breast cancer cell proliferation as PKD2 silencing does." (PMID 35805075, 2022). "A similar effect was observed in another breast cancer cell line, in that siRNA-mediated knockdown of PKD2 inhibited migration of MCF7 cells." (PMID 33807058, 2021). "Compared to consistent tumor‐suppressive functions of PKD1 in breast cancer, how PKD2/3 functions in breast cancer are not fully understood." (PMID 30652415, 2019). "The enrichment of pathway on cell cycle control upon silencing PKD2 or PKD2&3 gives a mechanistic explanation to the observation that silencing PKD2 or PKD3 inhibits proliferation of breast cancer cell and reduced breast tumor burden." (PMID 30652415, 2019). "In conclusion, in the current study, we reported the oncogenic functions of PKD2 and D3 in breast cancer and in regulating cancer‐related pathways to shed light on the oncogenic functions and mechanisms of PKDs in breast cancer." (PMID 30652415, 2019). "The enrichment of pathways on adherent junction and regulation of actin cytoskeleton gives mechanistic explanations to the observation that silencing PKD2 or PKD3 inhibits migration of breast cancer cells." (PMID 30652415, 2019). "In breast cancer all three isoforms (PKD1, PKD2 and PKD3) have been implicated in regulating cancer cell survival and proliferation during tumor formation." (PMID 30555634, 2018). "The identification of IL-11, as well as of MMP-1 and MMP-13, which are also mediators of breast cancer metastasis to the bone, supports the hypothesis that PKD2 and PKD3 contribute, via the secretome, to the colonization of the bone in TNBC." (PMID 38323010, 2024). "We conducted an analysis of PKD mRNA expression levels in breast cancer using the TCGA database that revealed a decrease in PKD1 expression and an increase in PKD3 expression, whereas PKD2 levels are unchanged in basal-like breast cancer compared with normal tissue." (PMID 37293129, 2023). "Specifically, both short hairpin RNA (shRNA)-mediated abrogation of HSP90 isoforms (HSP90ɑ and HSP90β) and pharmacologic inhibition of HSP90 by PU-H71 and STA-9090 resulted in decreased PKD2 protein levels and enhanced apoptosis in lung, pancreatic, and breast cancer cell lines." (PMID 33807058, 2021). "Furthermore, PKD2 was identified as an important regulator of drug resistance and P-glycoprotein expression in paclitaxel-treated breast cancer cells." (PMID 33807058, 2021). "In addition, PKD2 is involved in the development of various tumor types including pancreatic, colorectal, and breast cancer, glioma multiforme, and leukemia." (PMID 34249722, 2021).